GACAT1 (gastric cancer associated transcript 1)
Synonyms: LINC00876; AC096655.1-002
Gene: Long non-coding RNA gene on chromosome 2 (107,754,112 to 107,822,129, forward strand). Ensembl gene ENSG00000232991.
Diseases named in the same sentence as GACAT1 in open-access papers:
GACAT1 is named in the same sentence as 8 diseases in open-access papers, as found by Europe PMC text mining. Sharing a sentence is not in itself a finding about the gene and the disease. The quoted sentences say what the papers report.
gastric cancer (8 papers, 2014 to 2021). A primary or metastatic malignant neoplasm involving the stomach. "Gastric cancer-associated transcript 1 (GACAT1) gets its name from the fact that it was first found in gastric cancer." (PMID 34460438, 2021). "GACAT1 is significantly associated with lymph node metastasis and distant metastasis in gastric cancer tissues and may play an important role in gastric cancer metastasis." (PMID 32695786, 2020). "Recently, a new lnRNA, AC096655.1‐002 (GACAT1), was originally found to be correlated with progression of gastric cancer, and expression of GACAT1 was decreased in gastric cancer." (PMID 34378327, 2021). "HOTAIR, GCAT1 (gastric cancer-associated transcript 1), H19, and SUMO1P3 (small ubiquitin-like modifier SUMO 1 pseudogene 3) are the main lncRNAS reported as overexpressed in gastric carcinomas." (PMID 26448935, 2015). "The lncRNA gastric cancer associated transcript 1 (GACAT1), was found to be expressed at lower levels in gastric cancer tissues compared to corresponding normal tissues." (PMID 25101115, 2014). "However, Shi et al30 reported that GACAT1 was overexpressed in gastric cancer samples and GACAT1 overexpression induced gastric cancer cell growth, migration and invasion." (PMID 34378327, 2021). "Recently, a new lnRNA, GACAT1, has been firstly identified in gastric cancer." (PMID 34378327, 2021). "In addition, previous report showed that GACAT1 overexpression induced gastric cancer cell proliferation, migration and invasion through modulating miR‐149 expression." (PMID 34378327, 2021). "For example, decreased expression of gastric cancer-associated transcript 1 (GACAT1) is significantly associated with metastasis, invasion, and tissue differentiation in patients with GC." (PMID 26472090, 2015).
breast tumour (1 paper, 2021). "Wang et al35 indicated that GACAT1 induced breast tumour progression via sponging miR‐875‐3p." (PMID 34378327, 2021).
cancer (2 papers, 2021 to 2023). A tumor composed of atypical neoplastic, often pleomorphic cells that invade other tissues. "GACAT1 (the lncRNA gastric cancer-associated transcript 1) plays a carcinogenic role in different types of cancer." (PMID 36817434, 2023). "LncRNA GACAT1 was highly expressed in cancer tissues and cell lines of OSCC patients (P < 0.01), while miR-149 was low expressed (P < 0.01)." (PMID 34460438, 2021).
tumor (2 papers, 2021 to 2022). "Of 25 TSCC specimens, GACAT1 was overexpressed in 18 patients (18/25, 72%) compared to non‐tumour specimens." (PMID 34378327, 2021). "We proved that expression of GACAT1 was increased in TSCC specimens compared to non‐tumour specimens." (PMID 34378327, 2021). "Of 25 TSCC specimens, GACAT1 expression was overexpressed in 18 patients (18/25, 72%) compared to non‐tumour specimens." (PMID 34378327, 2021). "We observed that GACAT1 expression was overexpressed in TSCC cell lines (Tca8113, SCC1, SCC‐4 and SCC‐15) compared to non‐tumour specimen." (PMID 34378327, 2021).
GACAT1 also shares sentences with these, for which no sentence is quoted: breast carcinoma (1 paper); lymph node metastasis (1); oral squamous cell carcinoma (1); tongue squamous cell carcinoma (1).